INS (insulin)
Diseases named in the same sentence as INS in open-access papers (continued):
Sharing a sentence is not in itself a finding about the gene and the disease.
Hyperglycemia (continued). "As adipose tissue mass gain with insulin therapy is considered an adverse effect, it would be an advantage if future insulin therapies could dissociate adipose lipid gain from reduction of hyperglycemia." (PMID 24069458, 2013). "Finally, the hyperglycaemia/oxidative stress/inflammation axis is auto-perpetuating, as many inflammatory mediators impair insulin signaling, thus exacerbating hyperglycaemia and ROS production." (PMID 23698776, 2013). "In addition, correction of hyperglycemia by insulin treatment in diabetic rats normalized expression of brain Kir6.2, consequently prevented the exacerbating brain injury." (PMID 23991188, 2013). "These animals showed decreased pancreatic insulin and hyperglycemia (200–300 mg/dL)." (PMID 23878822, 2013). "IR is characterized by hyperglycemia and relative impairment of insulin secretion." (PMID 23339356, 2013). "In conclusion, the anesthetic xylazine can cause acute hyperglycemia with no significant alterations of blood insulin, glucagon, and GLP-1 in normoglycemic and insulin-dependent diabetic non-human primates." (PMID 24138083, 2013). "There may be reduced glucose oxidation which could result in impaired insulin secretion and delayed intracellular glucose removal with subsequent delayed cellular entry of glucose and resultant hyperglycaemia." (PMID 23424590, 2013). "Although the compensatory hyperinsulinemia prevents development of fasting hyperglycemia in insulin-resistant individuals, the increased level of circulating insulin directly and/or indirectly affects different molecular signaling and can promote prostatic growth." (PMID 24267821, 2013). "Indeed, recent studies revealed that leptin has the effect to normalize hyperglycemia and hyperinsulinemia and to increase insulin sensitivity." (PMID 23579596, 2013). "And the STZ-model is associated with severe hyperglycemia and hypoinsulinemia, which is not encountered in patients with type 1 diabetes receiving exogenous insulin." (PMID 23530831, 2013). "In the present study, differentiated islet-like structures derived from human fetal pancreatic progenitor cells could release insulin upon in vitro stimulation with glucose and corrected hyperglycemia in diabetic animals in vivo." (PMID 24268157, 2013). "Such hyperglycemia is detrimental to β cells and insulin target tissues, and this glucotoxicity is clinically relevant as a cause of diabetes-related complications such as nephropathy, retinal blindness, neuropathy, peripheral gangrene, and cardiovascular disease." (PMID 23573144, 2013). "Studies in rats have shown green tea extracts also reduce fasting hyperglycemia, regulate the expression of genes involved in glucose uptake and the insulin signal transduction pathways, scavenge free radicals, reduce oxidative stress, and have an anti-diabetic effect." (PMID 24260170, 2013). "Furthermore, PERK−/− mice are prone to hyperglycemia and diabetes, due to a reduction in insulin secretion." (PMID 24705207, 2013). "There is evidence that hyperinsulinaemia, hyperglycaemia and chronic inflammation may affect the neoplastic process through various pathways, including the insulin/IGF-1 pathway, and most cancer cells express insulin and IGF-1 receptors." (PMID 23801097, 2013). "When there are variations on meal sizes or insulin sensitivity, both insulin-only and prediction/suspending therapies are faced with increased hypoglycemia and hyperglycemia events; however, both P-type and PD-type therapies can keep all glucose concentrations within the safe range (70~180 mg/dL)." (PMID 24260042, 2013). "Because SIRT1 requires NAD for its enzymatic activity, a decline in NAD biosynthesis on high glucose or hyperglycemia may result in a significant reduction of SIRT1 levels and subsequent loss of the glucose- or insulin-responsive phenotypes." (PMID 23734259, 2013).
Hyperglycemia (continued). "We modelled the effect of hyperinsulinemia, free fatty acid and hyperglycemia on insulin signalling in cell culture by prolonged (16 h) treatment of C2C12 mouse myotubes with insulin (10 nM), saturated fatty acid (palmitate, 500 μM) or high glucose (25 mM, instead of 5.5 mM)." (PMID 23483710, 2013). "The present study was conducted to investigate the effects of hyperglycemia on inflammatory responses in acute lung injury induced by whole lung lavage and to compare the effects of pulmonary or intravenous administration of insulin on ongoing inflammatory responses in the lungs." (PMID 23622115, 2013). "In the current study hyperglycemia was induced following euglycemic insulin clamp with continued insulin infusion in insulin deficient type 1 diabetes so that insulin levels should not have changed." (PMID 22701470, 2012). "First, we tested whether the increase in CTGF levels with hyperglycemia could be attenuated through insulin therapy and whether this treatment affected the level of expression of key ECM molecules." (PMID 22511849, 2012). "Some authors have considered that supra-physiologic levels of exogenous insulin and hyperglycemia per se could be responsible for IR in T1D patients." (PMID 22792382, 2012). "The developmental plasticity theory, however, is able to reason that the hyperinsulinemia in the infant accompanying hyperglycemia in the mother programs the child to preferentially deposit adipose tissue leading to obesity and insulin insensitivity in later life." (PMID 22288007, 2012). "This work highlights the importance of physiological glucose levels when differentiating satellite cells into myocytes and provides evidence that hyperglycemia may promote both insulin and GLP-1 resistance in skeletal muscle." (PMID 22937169, 2012). "Hyperglycemia may directly influence breast cancer progression and outcomes via several mechanisms, including pathways mediated by high levels of insulin and insulin-like growth factors, sex hormones, and inflammatory markers." (PMID 22919369, 2012). "The authors investigated insulin secretion in offspring of late pregnancy hyperglycemia in rats." (PMID 23209676, 2012). "Therefore, it is unlikely that insulin affected the protective effect of preconditioning in these patients, and it is more likely that the hyperglycemia abolished this protective effect." (PMID 23051145, 2012). "This initial increase in poor outcomes was likely mediated by the fact that GIK infusion frequently induced hyperglycemia and volume overload, which may have mitigated the beneficial effects of insulin in the regimen." (PMID 22830071, 2012). "Previous research has suggested that stable expression of PDX-1 in adult human mesodermal tissues activated expression of all four islet hormones including insulin and reversed hyperglycemia in vivo, but more factors that stimulate cells further toward differentiated normal β-cells were needed." (PMID 22761608, 2012). "HIMP1 overexpression at relatively lower levels in L1 heterozygotes results in a negligible decline in blood glucose concentrations and an insignificant elevation in blood insulin levels, while HIMP1 overexpression at higher levels are toxic, causing hyperglycemia in L2/3 heterozygotes." (PMID 22470529, 2012). "This would lead to an increased cellular potassium uptake from the liver (and muscles) through a direct and an indirect mechanism (hepatic glycogenolysis → hyperglycemia → insulin hyperincretion → increased cellular uptake of glucose and potassium by way of membrane-bound Na/K ATPase stimulation)." (PMID 22536007, 2012). "This suggested that poor glycemic control might damage brain areas involved in learning and memory, thus limiting the analysis of insulin and hyperglycemia roles in diabetic brain." (PMID 22500228, 2012).
Hyperglycemia (continued). "Continuous glucose monitoring systems may help in this regard to prevent hypoglycemia and limit excursions into hyperglycemia by providing greater information to quantify insulin sensitivity and respond faster to changes in patient condition." (PMID 22871230, 2012). "These incur extensive or complete loss of pancreatic β-cells and the consequent lack of insulin thereby cause extreme hyperglycemia with glycosuria, polyuria, polydipsia, hyperphagia, and weight loss." (PMID 22899950, 2012). "In 2005, in a study conducted by Van den Berghe and colleagues, they showed that administration of insulin in order to prevent hyperglycemia in ICU kept the central and peripheral nervous system safe leading to shortening of ICU stay and consequently earlier remission after discharge." (PMID 24665266, 2012). "Postprandial hyperglycemia results from abnormal insulin secretion by β-cells in response to a meal, impaired hepatic glucose production, and defective glucose uptake by peripheral insulin-sensitive tissues, particularly the skeletal muscles." (PMID 22754367, 2012). "Under diabetic conditions, hyperglycemia per se and subsequent induction of oxidative stress decrease insulin biosynthesis and secretion, accompanied by reduction in expression and/or activities of insulin gene transcription factors PDX-1 and MafA." (PMID 23202973, 2012). "Reduced glucose intake might be feasible as an initial step targeting hyperglycemia in the early post-operative course of cardiac surgery in relatively stable children, potentially avoiding insulin use and its complications." (PMID 23031354, 2012). "The combination of prandial and basal insulin clearly results in better glycaemic control and less glucose variability.Multiple insulin dosing administration commencement in our patients with DM depends on the degree of hyperglycemia and the patient’s acceptance of multiple daily injections." (PMID 23199230, 2012). "If GLP-1-mediated glucose uptake in healthy skeletal muscle occurs via a mechanism similar to that of insulin, it can also be hypothesized that hyperglycemia may also result in impaired GLP-1-induced glucose uptake in human skeletal muscle." (PMID 22937169, 2012). "Furthermore, hepatocyte-selective genetic knockout of CB1R in mice led to reduced steatosis, hyperglycemia and insulin and leptin resistance on high-fat diet in the context of similar adiposity when compared to wild type mice on high-fat diet." (PMID 22870290, 2012). "Individuals newly diagnosed with PD display reduced insulin-mediated glucose uptake, which is hypothesized to be due to inhibit early insulin secretion and hyperglycemia after glucose loading." (PMID 22619734, 2012). "Therefore, a model of ALI with non-hyperglycemia and continuously infused human insulin by micro-osmotic pumps at a dose and a rate that maintained the glucose levels within normal range and did not worsen LPS-induced hypoglycemia were used in this study." (PMID 22458687, 2012). "Therefore, we administered multiple low doses of STZ to restrict the ability of pancreatic β-cells to increase insulin secretion, thereby generating hyperglycemia as previously reported." (PMID 22860063, 2012). "Hyperglycemia in Px rats was due to a concomitant decrease in serum insulin levels." (PMID 22550941, 2012). "Thus, a Port-A catheter can be used to transplant differentiated insulin-producing cells from human MSCs into the portal vein to alleviate hyperglycemia among diabetic rats." (PMID 22545626, 2012). "Constant maternal hyperglycemia limits, while pulsatile maternal hyperglycemia may enhance, fetal glucose-stimulated insulin secretion (GSIS) in sheep." (PMID 23133755, 2012). "In insulin treated patients the measurement of endogenous insulin secretion may help predict the degree of postprandial hyperglycaemia and the likely response to prandial insulin." (PMID 22681724, 2012).
Hyperglycemia (continued). "Similarly, in obese diabetic KK-Ay islets, the number of c-Jun-positive cells was increased with marked hyperglycemia, and both MafA and insulin protein levels were decreased in those cells." (PMID 23202973, 2012). "Thus, exenatide increases insulin production and secretion in response to hyperglycaemia, suppresses inappropriate plasma glucagon secretion, slows gastric emptying and decreases hepatic glucose production, all of which combine to lower blood glucose." (PMID 23061886, 2012). "We hypothesized that hyperglycemia-induced oxidative stress in the pancreatic beta cell may contribute to beta cell dysfunction and impaired insulin secretion because of deregulation in the expression of oxidative metabolism genes." (PMID 22454629, 2012). "Defects in the insulin-glucagon fine-tuning machinery may result in β-cell glucose incompetence, leading to unsuppressed glucagon secretion and subsequent hyperglycemia, which often occur under extreme conditions of glucose influx or efflux." (PMID 23316165, 2012). "In our study, the acute insulin response to the oral glucose load, which can be considered as a marker of β-cell function, was found to be decreased in non-alcoholic fatty liver disease patients with hyperglycemia." (PMID 21960993, 2012). "However in these subjects, the risk of hyperglycemia increases as a common adverse event originated by the normalization of GH and IGF-1 levels as well as the inhibition of insulin release by SST administration." (PMID 23162532, 2012). "Hyperglycemia may be controlled in different ways, such as dietary changes, the use of hypoglycemic agents, insulin, and through islet transplantation." (PMID 22355255, 2012). "Disrupted insulin signaling leads to hyperglycemia and dyslipidemia." (PMID 22680924, 2012). "Depending on its intensity, this response could either play an important role in beta-cell adaptation to increased insulin demand under physiological conditions (physiological hypoxia) or be involved in the detrimental effect of chronic hyperglycemia." (PMID 22235342, 2012). "Because manual calculation of insulin boluses is both complex and time consuming, people may rely on empirical estimates, which can result in persistent hypoglycaemia and/or hyperglycaemia." (PMID 23062116, 2012). "Results from animal and human studies indicated the hyperglycemia was associated with exacerbation of inflammation and promotion of injury in ALI and insulin treatment while maintaining euglycemia was found to attenuate the inflammatory response, reduce lung injury, and decrease the morbidity." (PMID 22458687, 2012). "Thus a vicious cycle of hyperglycemia and intermittent insulin administration results in glycogenosis." (PMID 23039762, 2012). "To validate 8-day cultivation in 30 mM glucose could mimic chronic hyperglycemia in vivo, we tested insulin secretion capability." (PMID 22509362, 2012). "Additionally, patients with hyperglycemia showed significantly higher insulin levels at time 0, 90, and 120 min compared with patients without hyperglycemia." (PMID 21960993, 2012). "However, the “functional” hepatocytes would be expected to play a critical role in the hepatic insulin synthesis, particularly when the pancreatic cells were destroyed for the control of hyperglycemia." (PMID 23675270, 2012). "In addition to increased α-cell sensitivity to insulin, chronic hyperglycemia plays an important role in dysregulation of α-cells but no effective treatment has been developed to increase (or regulate) glucagon secretion to combat hypoglycemic attacks." (PMID 22969729, 2012). "Conceivably, the sustained reversal of hyperglycemia may be achieved with a compensatory increase in insulin secretion as observed in the HF-fed mice in the present study or improved β-cell function as suggested for incretins." (PMID 22860063, 2012).
Hyperglycemia (continued). "These infants were significantly younger than the remainder of the study populations and displayed significant resistance to insulin and persistent hyperglycemia despite insulin infusions, resulting in a clinical decision to reduce the dextrose concentration of their parenteral nutrition infusions." (PMID 22871230, 2012). "A-ZIP transgenic mice (these animals are insulin-resistant and hyperlipidemic), which have a deficiency in MCP-1, displayed decreased hyperglycemia, hyperinsulinemia, and hepatomegaly; moreover, these mice had increased levels of markers for AAMφs, such as Arg1 and Chi313." (PMID 23326021, 2012). "Furthermore, autophagy has been reported to control insulin content and ubiquitin aggregate formation in response to oxidative stress or hyperglycemia in beta cells." (PMID 22563482, 2012). "Additionally, the half-life of blood glucose (T1⁄2) was raised by more than double by the MSG + ASP treatment in male subjects, indicative of longer periods of insulin-stimulated hyperglycemia following chronic treatment with both food additives combined." (PMID 22697049, 2012). "This might represent the establishment of a partial compensatory mechanism aimed at resisting hyperglycemia by increasing local insulin sensitivity." (PMID 22479501, 2012). "The finding may be incidental, however, it is consistent with generally higher use of insulin at the clinic where limited maternal education and understanding are thought to impact on poorer dietary adherence and higher rates of hyperglycaemia." (PMID 22988897, 2012). "Hyperglycemia may damage the microvasculature of the blood-brain barrier and/or modify insulin availability in the brain, disrupting normal brain function and cognition." (PMID 22509243, 2012). "However, treating high-fat-fed rats with a low dose of streptozotocin damages insulin producing β-cells so that hyperglycemia develops even though insulin levels are similar or even higher than in chow-fed normoglycemia rats." (PMID 22988492, 2012). "As the weight control is important for improving insulin sensitivity and reducing CVD risk, therefore it might be speculated that in apo E4 carriers weight control play crucial role in control of hyperglycemia and reducing CVD risk." (PMID 23497440, 2012). "Prandial fast acting exogenous insulin may have little impact on post meal hyperglycaemia above these levels." (PMID 22681724, 2012). "We tested the relationship between endogenous insulin secretion and post meal hyperglycaemia." (PMID 22681724, 2012). "An alternative approach to prevent hyperglycemia and avoid the use of insulin might be reducing intravenous (IV) glucose infusion to below current recommendations for glucose intake (approximately 5.0 mg/kg per minute)." (PMID 23031354, 2012). "It is noted, however, that since it remains unclear at this point whether the antioxidant treatment can have positive effects on insulin gene expression even in the presence of continuing hyperglycemia, further studies would be necessary to clarify this point." (PMID 23202973, 2012). "However, sliding scale regimens, defined as administration of a preestablished amount of rapid acting insulin in response to hyperglycemia, are ineffective." (PMID 20811546, 2011). "The amount of insulin produced was sufficient to reduce hyperglycemia in a diabetic mouse model." (PMID 22007286, 2011). "Hyperglycaemia was accompanied by elevations in plasma insulin." (PMID 21347323, 2011). "The hyperglycemia risk is not negligible, but thus far only mild rebound hyperglycemia and minimal ketonaemia have been reported after a temporary suspension of insulin administration." (PMID 22071283, 2011). "The HOMA-IR index, a simpler method to measure insulin sensitivity usually used in clinical and animal studies, was significantly decreased in AP-treated groups compared to the HF group, indicating that AP reduced hyperglycemia and hyperinsulinemia." (PMID 21799697, 2011).